NGFR (nerve growth factor receptor)
Diseases named in the same sentence as NGFR in open-access papers (continued):
Sharing a sentence is not in itself a finding about the gene and the disease.
melanoma (continued). "These cells were naïve to immune checkpoint inhibitors, and we examined whether the expression of key IFNγ downstream targets [PD-L1, PD-L2, nerve growth factor receptor (NGFR), HLA-A, -B, -C, and HLA-DR] could serve to assess the integrity of IFNγ signaling in melanoma." (PMID 29977240, 2018). "Furthermore, enforced expression of recombinant IL32α, -β, or -γ in M397 did not impact expression of melanoma differentiation genes MITF, AXL, NGFR or MLANA, strongly suggesting that IL32 is not a causal or upstream event in the melanoma dedifferentiation process." (PMID 30953519, 2019). "Nonetheless, 90 days of exposure of melanoma cells to BRAF inhibitors displays no multidrug resistance, leading to the elimination of IDTC markers such as NGFR and KDM5B and permanent resistance." (PMID 36224606, 2022). "Although we did not perform statistical analyses on the three transitory melanoma cell lines, TNFα clearly reduced both MITF and Melan A levels and concurrently increased NGFR and AXL expression in this melanoma subtype." (PMID 34073253, 2021). "Thin primary melanomas (such as MM28, Breslow = 0.8 mm) or thick primitive melanomas (such as MM25, Breslow = 16 mm) displayed a proliferative/differentiated ZEB2+ MITF+ SOX10+ phenotype with no or low ZEB1, SOX9 and NGFR expression." (PMID 38519642, 2024). "Regardless of genomic classification, melanoma can switch from a proliferative and differentiated phenotype (marked by high MITF expression) to an invasive and dedifferentiated phenotype (characterized by low MITF and neural crest stem cell markers such as NGFR)." (PMID 40806546, 2025). "Also, the relationship between MITF and NGFR remains unclear: While NGFR expression is elevated in melanoma with low MITF and has been identified as a direct target of MITF, we have not observed a consistent effect of NGFR overexpression on MITF expression in tumors in vivo." (PMID 36638181, 2023).
Alzheimer disease (57 papers, 2008 to 2026). A progressive, neurodegenerative disease characterized by loss of function and death of nerve cells in several areas of the brain leading to loss of cognitive function such as memory and language. "The present study mainly aims to investigate the association between genetic polymorphism of NGFR and the risk of Alzheimer's disease." (PMID 36074475, 2022). "Furthermore, inherited rs734194 polymorphism of NGFR gene was associated with the decreased risk of obsessive-compulsive disease, schizophrenia and Alzheimer’s disease." (PMID 29499660, 2018). "Loss of basal forebrain cholinergic neurons is attributable to the proapoptotic signaling induced by nerve growth factor receptor (NGFR) and may link to Alzheimer's disease (AD) risk." (PMID 22236693, 2012). "Our study identified Slc22a17 as a potential drug target to design therapies for interventions to enhance neurogenesis in Alzheimer’s disease and proposed additional candidate genes potentially functioning in the NGFR/p75NTR pathway." (PMID 37429840, 2023). "Very interestingly, NTRK1/NTRKA protein levels are reduced in the cortex of Alzheimer’s disease patients, while many studies report no change in p75/NGFR levels." (PMID 32575701, 2020).
breast carcinoma (43 papers, 2006 to 2025). "Nevertheless, in the case of NGFR it had been previously shown that it can be used as a marker for basal-like breast carcinomas associated with good prognosis, which was in agreement with our results in the MicMa cohort." (PMID 26673618, 2016). "Furthermore, the NGF receptor (NGFR), which has been implicated in breast cancer invasion and metastasis, was significantly downregulated across the three solid stress pressures." (PMID 40371393, 2025). "In addition to the expression of NGF, the expression of NGFR was also associated with progressive factors of breast carcinomas, such as HER2 expression, estrogen receptor negativity, and higher histologic grade." (PMID 28679437, 2017). "Studies in breast cancer, colorectal cancer, and glioblastoma suggest that NGFR possesses tumor suppressor gene capabilities; however, other studies have suggested that NGFR overexpression promotes tumor cell invasion and migration in metastatic cancers." (PMID 40732340, 2025). "Research has also shown that TrkA and NGFR/p75NTR receptors are overexpressed in most types of breast cancer compared to normal cells." (PMID 36354700, 2022). "The elevated co-expression of NGFR, EFNB1, and APP was associated with longer overall and metastasis-free survival of patients with breast cancer." (PMID 30446011, 2018). "An oncogenic role of NGF has been supported by reports that NGF and NGFR participate in the progression of various human cancers, such as breast cancer, ovarian cancer, pancreatic cancer, oral carcinoma, and salivary gland cancer." (PMID 28679437, 2017). "In breast cancer studies using breast cancer cell lines had shown that NGFR signalling regulates breast cancer cells survival." (PMID 26673618, 2016). "Whilst we observed higher NGF downstream gene transcripts, the minimal Log2 fold increase of NGF and the stark downregulation NGFR persuaded us to look for other significantly upregulated genes and pathways that are biologically relevant to breast cancer metastasis." (PMID 40371393, 2025). "In addition to NGF, NGFR/p75NTR and TrkA receptors are also expressed in breast cancers cells, either at the transcriptional or protein level." (PMID 36354700, 2022). "In addition to NGF and TrkA, other researchers targeted NGFR/p75NRT signaling pathways for the treatment of breast cancer." (PMID 36354700, 2022). "In addition, NGFR was reported to be a potential biomarker for molecular subtypes of breast cancer, including basal-like breast cancer and luminal B breast cancer." (PMID 30355311, 2018). "Several examples of in vitro and in vivo evidence show that NGF is both synthesized and released by breast cancer cells, and has mitogen, antiapoptotic and angiogenic effects on these cells through the activation of different signaling cascades that involve TrkA and NGFR/p75NTR receptors." (PMID 36354700, 2022). "Based on transcriptomic analysis, we expect to further investigate the molecular mechanisms of metochalcone that involve the NGFR-AMPK-mTOR pathway in lung cancer and METTL7A-mediated RNA m6a methylation and ferroptosis in breast cancer." (PMID 38686052, 2024). "Cells with ectopic NGFR-EGFR-FRB and NGFR-Erbb2-FKBP were selected subclonally for expression at levels comparable to endogenous EGFR and ERBB2 in breast cancer lines." (PMID 37055441, 2023). "NGF is involved in the proliferation of breast cancer cells through the NGFR TrkA-MAPK pathway and it prevents apoptosis by activating the NGFR p75NTR-NFκB pathway." (PMID 28679437, 2017).
breast carcinoma (continued). "The expression of key markers associated with proliferation (MKI67, PCNA, CCNB1, MYBL2, BUB1, CCND1), apoptosis (BCL2, CASP7, CASP8, CASP9, CASP3, BAX, APAF1), differentiation (CDH1, CD24, EPCAM, ESR1, NGFR, RUNX1), and breast cancer stemness (CD44, ITGA6, DNER, ALDH1A3, ABCG2, PROCR) was assessed." (PMID 35183258, 2022). "The binding of ligand NGF with tropomyosin receptor tyrosine kinases A (TrkA) and the TNF-receptor family member p75NTR (NGFR) activates downstream pathways, such as RAS/MAPK and PI3 kinase, resulting in increased cell proliferation and survival of human breast cancer cells." (PMID 34771423, 2021). "MCF-7, T47-D, BT-20, and MDA-MB-231 breast carcinoma cells secrete NGF and express NGFR; when NGF combines with TrkA, an intracellular signal is sent via p21ras by phosphorylation and the ras-MAPK signal pathway is stimulated to influence gene transcription, translation and mediate cell growth." (PMID 22217202, 2012). "To understand mechanistically how CARM1 might be regulating NGFR signaling we used an antibody and mass spectrometry approach to define the known CARM1 substrates in NSC11 GSCs—a method previously used to identify CARM1 substrates in human breast cancer cells." (PMID 40321217, 2025).
glioma (39 papers, 2008 to 2025). A benign or malignant brain and spinal cord tumor that arises from glial cells (astrocytes, oligodendrocytes, ependymal cells). "Several independent data supporting a strong association with NGFR and high-grade glioma have been established by the Repository of Molecular Brain Neoplasia Data (REMBRANDT), the TCGA, and the Human Protein Atlas where NGFR has been shown to be elevated at both the RNA and protein level." (PMID 35280742, 2022). "As its name implies, NGFR is an important signaling receptor for the development, maintenance, and growth of both normal neural tissues and gliomas." (PMID 38612480, 2024). "In glioma, although NGFR is also upregulated, the empty binding status ultimately induces remodeling of actin cytoskeleton that potentiates glioma cells for invasiveness." (PMID 37509718, 2023). "CASZ1 also enhances the proliferation and invasion of glioma cells by directly upregulating NGFR (i.e., p75NTR), which is considered an oncogene for glioma." (PMID 37509718, 2023). "Among those relative downregulated genes, NGFR, which had been confirmed to play a crucial role as a cancer promoter in glioma, was focused on." (PMID 35280742, 2022). "In vitro assays suggests that upregulation of the phosphorylation of p65 resulting from NGFR overexpression can drive proliferation and invasion in human glioma cells." (PMID 35280742, 2022). "Our results showed that FN1, ITGA5, OSMR, and NGFR were overexpressed in TCGA-GBM, suggesting that these genes were not only prognostic but also diagnostic between high-grade gliomas and normal brain tissue." (PMID 35954323, 2022). "NGFR-expressing glioma cells in humans enhance migration, induce structural rearrangement of the actin cytoskeleton, and reduce RhoA activity, which are closely related to cell invasion." (PMID 35954323, 2022). "Knocking down NGFR expression decreased cell proliferation rates and the invasive ability of high invasive glioma cells." (PMID 35280742, 2022). "Consistently, NGFR was more highly expressed in human glioma tissues compared to adjacent tissues as determined by immunoblotting (IB)." (PMID 27282385, 2016). "Since NFIA specifically has been shown to be significantly involved in Glioma tumorigenesis we hypothesized NFIA to be the primary CARM1 substrate responsible for regulating NGFR signaling in GSCs." (PMID 40321217, 2025). "Cancer proliferation and invasion genes were downregulated, including proliferation marker gene MKI67 with prognostic value in glioma, nerve growth factor receptor NGFR involved in GBM invasion, and long non-coding RNA MALAT1 with tumor suppressive function in GBM." (PMID 38177502, 2024). "Our phenotypic and molecular data suggest that increasing NGFR expression in glioma cells may promote proliferation and invasion." (PMID 35280742, 2022). "However, the exact mechanism of LMO1 regulating NGFR transcription in mediating glioma invasion and progression still needs to be explored." (PMID 35280742, 2022). "A moderate positive correlation existed between the LMO1 expression and NGFR in glioma patients." (PMID 35280742, 2022). "Additionally, immunohistochemical (IHC) staining of human gliomas and their adjacent normal tissues exhibited hyperexpression of NGFR in the tumor tissues." (PMID 27282385, 2016). "Contrary, NGFR can induce invasion and metastasis in glioma and melanoma." (PMID 22558167, 2012). "Furthermore, using specific primers, we succeeded to detect the endogenous expression of mir-6165 in several glioma cell lines and glioma primary tumors known to express NGFR." (PMID 22558167, 2012). "Furthermore, NGFR was found to be highly expressed in 68.75% (33/48) of human gliomas examined." (PMID 27282385, 2016). "Based on further validation using the Chinese Glioma Genome Atlas (CGGA) database, we identified FN1, ITGA5, OSMR, and NGFR as stiffness-dependent prognostic genes." (PMID 35954323, 2022).
glioma (continued). "After validation using the Chinese Glioma Genome Atlas (CGGA) database, we further identified four stiffness-dependent prognostic genes: FN1, ITGA5, OSMR, and NGFR." (PMID 35954323, 2022). "Considering the clinical factors of glioma, these parameters (LMO1 and NGFR expression level, age, gender, WHO grade, IDH status and 1p/19q co-deletion) were included in the predictive model." (PMID 35280742, 2022). "Four stiffness-dependent prognostic genes (FN1, ITGA5, OSMR, and NGFR) were identified from GSE158097 and TCGA glioma datasets using bioinformatics analysis." (PMID 35954323, 2022). "Given that the increase in NGFR levels can significantly elevate the phosphorylation of p65 in LMO1 KD cells, this mean that LMO1 may be a key regulator of glioma proliferation and invasion." (PMID 35280742, 2022). "Taken together, these data revealed that NGFR, which was upregulated by LMO1 in glioma, may induce poor prognosis." (PMID 35280742, 2022).
neuroblastoma (34 papers, 2011 to 2025). Neuroblastoma (NB) is the most common solid, extracranial childhood tumor. "Loss of H3K27 methylation upregulates CLU and NGFR, induces apoptosis, and potentiates resveratrol-induced cell death in neuroblastoma cells." (PMID 37345170, 2023). "For example, CASZ1 suppresses NB partially due to upregulation of NGFR, which encodes a Fas/TNF-R family receptor that mediates apoptosis of neuroblastoma cells in the presence of nerve growth factor (NGF)." (PMID 37509718, 2023). "In line with our findings, previous studies have reported bFGF to increase the gene and protein expression of p75 NGFR in the human neuroblastoma cell line and expressions of GFAP mRNA in astrocytes." (PMID 32575426, 2020). "As for TRKA, the expression of NGFR is strongly down-regulated in aggressive neuroblastoma having MYCN overexpression." (PMID 23482921, 2013). "On the other hand, NGF promotes apoptosis in human SK-N-MC neuroblastoma cells expressing nerve growth factor receptor (p75NTR/NGFR) but not TRKA; however, it does not cause the death of human IMR32 neuroblastoma cells expressing TRKA but not p75NTR." (PMID 41189817, 2025). "Whether NGFR upregulation is instrumental and causal for the enhanced expression of NTRK2, NEFL, TUBB3, and MAP2 that we observe in the L-AN-5 neuroblastoma system, remains to be investigated." (PMID 33174841, 2020). "MiR-137 targets the EZH2 3′UTR in neuroblastoma cells, leading to decreased H3K27 methylation in the genomic regions of tumor suppressor genes clusterin (CLU) and nerve growth factor receptor (NGFR)." (PMID 37345170, 2023). "Of note, p75NTR (also known as NGFR), which is a representative marker of favorable prognosis in patients with neuroblastoma, is also silenced by EZH2." (PMID 36831211, 2023). "With regard to NGFR, the present study provides evidence that one mechanism by which VPA upregulates p75NTR expression involves the depletion of the PRC2 core component EZH2 and the consequent derepression of CASZ1, a neuroblastoma tumour suppressor and a positive regulator of NGFR." (PMID 32712736, 2020). "Also, we validated the interaction between endogenous NGFR and MDM2 in human neuroblastoma SK-N-SH cells that sustains high level of NGFR." (PMID 27282385, 2016).
Cognitive impairment (28 papers, 2013 to 2026). Abnormal cognition is characterized by deficits in thinking, reasoning, or remembering. "Of the top 10 most significant proteins, six (PLOD1, MFN2, NGFR, PPP2R5E, C4A/C4B, and ITGAV) have previously been linked to AD and/or cognitive function, underscoring their potential as biomarkers of cognitive impairment." (PMID 42253369, 2026). "Moreover, Crispoltoni and collaborators examined the relationship between the plasma levels of NGF as well as the expression levels of TrkA and NGFR/p75NTR in monocytes of patients with mild cognitive impairment (MCI), mild and severe AD." (PMID 36834612, 2023). "Similarly, chungkookjang stimulated nerve growth factor secretion and nerve growth factor receptor signaling pathway in Tg2576 mice and in trimethyltin-induced cognitive defective mice." (PMID 31344808, 2019). "Abnormalities in NGF signaling caused by disruption of the structure of its receptors [TrkA (NTRK1 gene) and p75 (NGFR gene)] or the signaling pathways involved, may also impair brain morphogenesis and lay the groundwork for the onset of mental and cognitive disorders." (PMID 38646100, 2024).
depression (27 papers, 2011 to 2025). "A transcriptome analysis showed that PAS840 upregulated the BDNF/VGF/NGFR pathway and increased neurotrophic nutrition to promote neurological function recovery and attenuate the risk of IS-induced depression." (PMID 39679371, 2024). "The NGFR gene encodes the p75 neurotrophin receptor, which regulates neuronal growth, survival and plasticity, and was reported to be associated with depression, schizophrenia and antidepressant efficacy in human patient and animal studies." (PMID 36291307, 2022). "NGFR gene polymorphisms were reported to be associated with depression, schizophrenia and antidepressant efficacy." (PMID 36291307, 2022). "As for NGFR rs2072446, it was observed as being associated with depression and schizophrenia." (PMID 29499660, 2018). "Four NGFR SNPs were detected based on a study among 1010 schizophrenia patients, 610 patients with major depressive disorders (MDD) and 1034 normal controls, respectively." (PMID 36291307, 2022). "Clinical studies on serum NGFR protein levels in patients also suggest the potential role of proBDNF/NGFR signaling in the pathogenesis of depression." (PMID 36291307, 2022). "Studies showed that the serum NGFR levels in patients with depression, schizophrenia and bipolar disorder were significantly different from those in healthy controls." (PMID 36291307, 2022). "Our study suggests that the effects of NGFR polymorphisms are not consistent with each other among psychiatric disorders, including schizophrenia, bipolar disorder and depression." (PMID 36291307, 2022). "The NGFR was reported to have protective effect against the development of depressive disorder." (PMID 21494644, 2011).
prostate carcinoma (25 papers, 2010 to 2026). A carcinoma that arises from epithelial cells of the prostate gland. "NGF can interact with two receptors, TrkA and NGFR, which were found in several types of cancer, including prostate cancer; they both play a role in prostate cancer progression." (PMID 40243726, 2025). "Metformin also appears to exert anti-tumor effects by inhibiting proteolysis of NGFR, a transmembrane protein involved in cell proliferation and metastasis in prostate cancer and HNSCC." (PMID 41156128, 2025). "MiR-330 is reported to induce apoptosis in prostate cancer cells through E2F1-mediated suppression of Akt phosphorylation, and in our subnetwork NGFR (also known as P75NTR) is the target of miR-330." (PMID 21931774, 2011). "In addition to NTRK1 and the NGFR, we identified a mechanism which is involved in ADT-mediated neuroendocrine differentiation in prostate cancer via CHRM4 upregulation." (PMID 33398073, 2021). "This suggests that NTRK1 and the NGFR might not respond to AR signaling, and the roles of NGF–NGFR or NGF–NTRK1 signaling pathways might differ from that of NGF–CHRM4 signaling in prostate cancer." (PMID 33398073, 2021).